JSRP1 (junctional sarcoplasmic reticulum protein 1)
Description:
Involved in skeletal muscle excitation/contraction coupling (EC), probably acting as a regulator of the voltage-sensitive calcium channel CACNA1S. EC is a physiological process whereby an electrical signal (depolarization of the plasma membrane) is converted into a chemical signal, a calcium gradient, by the opening of ryanodine receptor calcium release channels. May regulate CACNA1S membrane targeting and activity.
Synonyms: JP-45; JP45; FLJ32416
Tractability: PROTAC: ubiquitination databases record sites on it.
Gene: Protein-coding gene on chromosome 19 (2,252,074 to 2,269,759, reverse strand). Ensembl gene ENSG00000167476.
Subcellular location: Sarcoplasmic reticulum membrane; Endoplasmic reticulum membrane
Subcellular location (Human Protein Atlas): Endoplasmic reticulum
Gene Ontology:
Molecular function: protein binding
Biological process: skeletal muscle contraction
Cellular component: sarcoplasmic reticulum; endoplasmic reticulum membrane; sarcoplasmic reticulum membrane
Genetic constraint (gnomAD): Loss-of-function variants: 29 observed, 17.66 expected, observed/expected ratio (o/e) 1.64, 90% interval 1.2 to 1.95. The upper end of that interval is the gene's LOEUF score, 1.95, which puts it in group 6 of 6, group 1 being the genes least tolerant of losing a copy. Missense variants: 528 observed, 428.47 expected, observed/expected ratio (o/e) 1.23, 90% interval 1.15 to 1.32. Synonymous variants: 221 observed, 187.62 expected, observed/expected ratio (o/e) 1.18, 90% interval 1.05 to 1.32.
Homologues: Orthologues: chimpanzee JSRP1 (98% identical), macaque JSRP1 (92% identical), pig JSRP1 (67% identical), rat Jsrp1 (54% identical), mouse Jsrp1 (54% identical), guinea pig JSRP1 (53% identical).
Diseases named in the same sentence as JSRP1 in open-access papers:
JSRP1 is named in the same sentence as 6 diseases in open-access papers, as found by Europe PMC text mining. Sharing a sentence is not in itself a finding about the gene and the disease. The quoted sentences say what the papers report.
dilated cardiomyopathy (1 paper, 2025). Cardiomyopathy which is characterized by dilation and contractile dysfunction of the left and right ventricles. "Junctional sarcoplasmic reticulum protein 1 (JSRP1) is upregulated in a mouse model of dilated cardiomyopathy." (PMID 41462954, 2025).
lung adenocarcinoma (1 paper, 2022). A carcinoma that arises from the lung and is characterized by the presence of malignant glandular epithelial cells. "In this case report, we identified a novel nonreciprocal ALK fusion, namely, junctional sarcoplasmic reticulum protein 1 (JSRP1) intergenic region-ALK fusion (Jintergenic: A20) via next-generation sequencing in a female patient initially diagnosed with stage IV B lung adenocarcinoma." (PMID 36267987, 2022).
Obesity (1 paper, 2021). Accumulation of substantial excess body fat. "For SAT, the amount of DE mRNAs of obesity was 185 (50 for overweight, 54 for obesity, and 107 for obesity with MS), and only 3 mRNAs (JSRP1, MRS2 and STK40) were shared by all these 3 obesity components as shown in Venn diagram." (PMID 34621242, 2021).
JSRP1 also shares sentences with these, for which no sentence is quoted: cancer (1 paper); hepatocellular carcinoma (1); periodontitis (1).